RGS10 (regulator of G protein signaling 10)
Diseases named in the same sentence as RGS10 in open-access papers (continued):
Sharing a sentence is not in itself a finding about the gene and the disease.
Insulin resistance (2 papers, 2024 to 2025). Increased resistance towards insulin, that is, diminished effectiveness of insulin in reducing blood glucose levels. "RGS10-deficient mice exhibit impaired glucose tolerance, and high-fat diet induces insulin resistance in these mice." (PMID 38812790, 2024). "RGS10 deficient mice also exhibit insulin resistance and systemic inflammation." (PMID 38812790, 2024). "Animal studies have shown that RGS10 can help maintain metabolic homeostasis by mitigating inflammatory responses, which in turn reduces insulin resistance." (PMID 40296871, 2025). "RGS10 plays a key role in microglia activation and RGS10 knockout mice fed with high-fat diet display glucose intolerance and insulin resistance." (PMID 38812790, 2024).
osteopetrosis (2 papers, 2021 to 2022). Osteopetrosis, also known as marble bone disease, is a descriptive term that refers to a group of rare, heritable disorders of the skeleton characterized by increased bone density on radiographs. "Different from RGS4, the deletion of RGS10 or RGS12 in osteoclasts causes osteopetrosis phenotype through controlling the calcium oscillations and oxidative stress mediated Nrf2/Keap1 signaling pathways in mice, indicating their positive regulation in aging mediated osteoporosis." (PMID 35573989, 2022). "Compared to RGS10, conditional knockout of RGS12 in osteoclast lineage (CD11b-Cre and Mx1-Cre) also caused osteopetrosis phenotype." (PMID 35573989, 2022).
acute myeloid leukemia (1 paper, 2024). Acute myeloid leukemia (AML) is a group of neoplasms arising from precursor cells committed to the myeloid cell-line differentiation. "RGS10 has been linked to a poor prognosis in patients with laryngeal cancer, liver cancer, and childhood acute myeloid leukemia." (PMID 39145770, 2024).
age-related maculopathy (1 paper, 2013). "In humans, susceptibility genes for age-related maculopathy (ARM), a photoreceptor degenerative disease associated with microgliosis, map to the same region of human chromosome 10q26 as the RGS10 gene, suggesting that loss of RGS10 may predispose an organism to neurodegenerative disease." (PMID 24278459, 2013).
alveolitis (1 paper, 2021). "Altogether, the absence of Rgs10 is associated with increased tissue damage, bronchiolitis, alveolitis and general inflammation in influenza-infected mice." (PMID 34912341, 2021). "More importantly, at 5 dpi, Rgs10-/- mice developed severe lung damage demonstrated by massive inflammatory cell infiltration, such as neutrophils, into the bronchioles (bronchiolitis) and inflammatory cells aggregation into the alveolar walls and spaces (alveolitis)." (PMID 34912341, 2021).
autoimmune disease (1 paper, 2016). A disorder resulting from loss of function or tissue destruction of an organ or multiple organs, arising from humoral or cellular immune responses of the individual to their own tissue constituents. "Our novel findings demonstrate a critical role for RGS10 in mediating autoimmune disease through regulation of lymphocyte function." (PMID 26831924, 2016).
Autoimmunity (1 paper, 2016). The occurrence of an immune reaction against the organism's own cells or tissues. "We hypothesized that RGS10 modulates CNS autoimmunity by regulating T lymphocyte infiltration and/or effector functions." (PMID 26831924, 2016).
breast carcinoma (1 paper, 2024). "The mechanisms underlying the metastasis-suppressing function of RGS10 in breast cancer remain to be elucidated." (PMID 39145770, 2024). "In breast cancer samples from the Kaplan–Meier plotter database, high RGS10 mRNA level was associated with significantly improved DFS (p=0.0066) and OS (p=0.027)." (PMID 39145770, 2024). "RGS10 protein levels were significantly lower in breast cancer tissues compared to normal breast tissues, and deficiency in RGS10 protein predicted a worse prognosis in patients with breast cancer." (PMID 39145770, 2024). "RGS10 expression was associated with molecular subtypes of breast cancer, distant metastasis, and survival status." (PMID 39145770, 2024). "This suggests low RGS10 expression is associated with poor survival in patients with breast cancer." (PMID 39145770, 2024). "In breast cancer, RGS10 is downregulated in heavily metastatic human breast cancer cell populations compared to weakly metastatic human breast cancer cell populations." (PMID 39145770, 2024). "Patients with high compared to low RGS10 mRNA expression in breast cancer tissues had improved DFS and OS." (PMID 39145770, 2024). "The novel action of RGS10 in EMT in breast cancer appears to be dependent on LNC2, also known as neutrophil gelatinase-associated lipocalin, siderocalin, uterocalin, and oncogene 24p3." (PMID 39145770, 2024). "The luciferase reporter assay identified MIR539-5p as a miRNA that targets RGS10 in breast cancer cells." (PMID 39145770, 2024). "RGS10 protein levels were lower in the highly aggressive breast cancer cell line MDA-MB-231 compared to the poorly aggressive and less invasive breast cancer cell lines MCF7 and SKBR3." (PMID 39145770, 2024). "The MIR539-5p/RGS10/LCN2 pathway was identified as an important regulatory axis of EMT in breast cancer." (PMID 39145770, 2024). "In this study, we investigated the function of RGS10 in breast cancer, specifically in breast cancer metastasis." (PMID 39145770, 2024). "In conclusion, the results of this study show that RGS10 expression is related to survival outcomes in patients with breast cancer." (PMID 39145770, 2024). "RGS10 reduced breast cancer cell proliferation, colony formation, invasion, and migration by inhibiting EMT via a novel mechanism dependent on LCN2 and MIR539-5p." (PMID 39145770, 2024). "To investigate the biological role and clinical and prognostic significance of RGS10 in breast cancer tissues, we used survival analyses." (PMID 39145770, 2024). "Biochemical characterization of the molecular mechanisms of RGS10 in breast cancer should provide additional insight into the potential of RGS10 as a biomarker of EMT, metastasis, and prognosis in breast cancer and the role of RGS10 as a therapeutic target." (PMID 39145770, 2024). "To characterize RGS10 protein expression in the breast cancer cell lines MDA-MB-231, MCF7, and SKBR3, we conducted western blotting." (PMID 39145770, 2024). "Based on these findings, for the first time, we propose a MIR539-5p/RGS10/LCN2 regulatory axis in breast cancer." (PMID 39145770, 2024). "We evaluated the effects of RGS10 on breast cancer cell proliferation, colony formation, migration, and invasion in RGS10-depleted (shRNA-RGS10-506, shRNA-RGS10-161) SKBR3 cells and SKBR3 cells transfected with shRNA-negative control (NC)." (PMID 39145770, 2024). "RGS10 was expressed at lower levels in breast cancer tissues than in adjacent normal breast tissues." (PMID 39145770, 2024). "This pattern implied a downregulation of RGS10 expression in breast cancer tissues." (PMID 39145770, 2024). "To explore the mechanisms by which RGS10 suppresses breast cancer invasion and metastasis, we analyzed potential downstream tumor metastasis-related genes by comparing the transcriptomes in RGS10-depleted (shRNA-RGS10-506, shRNA-RGS10-161) SKBR3 cells and SKBR3 cells transfected with shRNA-NC." (PMID 39145770, 2024).
breast carcinoma (continued). "To study the upstream regulatory mechanism of RGS10 in breast cancer, we used the StarBase database to predict miRNAs that could potentially bind to RGS10." (PMID 39145770, 2024). "Taken together, these findings imply that RGS10 has a role in suppressing breast cancer and RGS10 may represent a potential prognostic biomarker in breast cancer." (PMID 39145770, 2024). "These in vivo data confirm the previous in vitro observations that RGS10 deficiency promotes invasion and metastasis by activating the LCN2 pathway to induce EMT in breast cancer cells, and demonstrate that RGS10 has utility as a prognostic biomarker in breast cancer." (PMID 39145770, 2024). "Finally, we applied RT-qPCR in freshly resected breast cancer tissues (n = 20) and matched adjacent normal breast tissues, and showed RGS10 mRNA levels were lower in breast cancer tissues compared to normal breast tissues (p=0.003)." (PMID 39145770, 2024). "The present study identifies RGS10 as an important mediator of EMT in breast cancer." (PMID 39145770, 2024). "Second, the mechanism by which the MIR539-5p/RGS10/LCN2 axis may be related to outcomes in patients with breast cancer remains to be elucidated." (PMID 39145770, 2024). "The regulation of EMT in breast cancer by RGS10 may rely on upstream regulation by MIR539-5p." (PMID 39145770, 2024). "To investigate the role of RGS10 in breast cancer cells, we silenced RGS10 in SKBR3 cells using two independent shRNA constructs, shRNA-RGS10-161 and shRNA-RGS10-506, which had significantly improved transfection efficiency compared to shRNA-RGS10-321." (PMID 39145770, 2024). "The ability of RGS10 to suppress EMT and metastasis in breast cancer was dependent on lipocalin-2 and MIR539-5p." (PMID 39145770, 2024). "This study identified a novel role for RGS10 in EMT and metastasis in breast cancer." (PMID 39145770, 2024).
colitis (1 paper, 2021). Inflammation of the colon. "RGS10 deficiency increased baseline intestinal inflammation, colitis severity, and neuropathology." (PMID 34412704, 2021). "A more pronounced genotype impact was seen in the DAI of DSS colitis; male (p = 0.0006) and female (p < 0.0001) RGS10−/− mice developed more severe and more persistent colitis than WT mice." (PMID 34412704, 2021). "RGS10−/− mice also developed more severe DSS-induced colitis that resolved more slowly than WT mice." (PMID 34412704, 2021). "TH protein levels were significantly reduced by MPTP in males and females as well as by colitis alone in male mice compared to RGS10+/+ H2O-Saline levels." (PMID 34412704, 2021). "The effects of colitis appeared to layer with those of MPTP and RGS10 deficiency." (PMID 34412704, 2021). "The colitis-associated increase in the ratio of phosphorylated to total TH was also mitigated in RGS10+/+ but not RGS10−/− male mice." (PMID 34412704, 2021). "In the absence of CD8+ T-cells, differences in colitis severity between RGS10+/+ and RGS10−/− mice were minimal." (PMID 34412704, 2021). "Indeed, this study found increased Cd8b expression in colon tissue of male mice following acute colitis but more modest changes in females which only reached statistical significance in females lacking RGS10." (PMID 34412704, 2021).
colorectal cancer (1 paper, 2024). A primary or metastatic malignant neoplasm that affects the colon or rectum. "RGS10 is a critical regulator of cell survival, polarization, adhesion, chemotaxis, and differentiation that exhibits tumor-suppressing effects in ovarian and colorectal cancer." (PMID 39145770, 2024). "In colorectal cancer, RGS10 expression is suppressed, and inhibition of DNA methylation may contribute to improved prognosis." (PMID 39145770, 2024).
diabetic retinopathy (1 paper, 2025). "Additionally, RGS10 is recognized as a significant immune-related target in diabetic retinopathy." (PMID 40296871, 2025).
dopaminergic neuroblastoma (1 paper, 2013). A neuroblastoma associated with increased dopamine excretion. "We found that conditioned media from LPS-treated Rgs10-/- macrophages exerted higher cytotoxicity on MN9D dopaminergic neuroblastoma cells." (PMID 24278459, 2013).
experimental autoimmune encephalomyelitis (1 paper, 2016). An autoimmune demyelinating disease of the central nervous system that is produced experimentally in animals by the injection of homogenized brain or spinal cord in Freund's adjuvant. "To define potential roles for RGS10 in regulating autoimmune responses, we evaluated RGS10-null and wild-type (WT) mice for susceptibility to experimental autoimmune encephalomyelitis (EAE), a widely studied model of MS." (PMID 26831924, 2016). "In this study, we investigated the role of RGS10 in T cells in the mouse experimental autoimmune encephalomyelitis (EAE) model of MS." (PMID 26831924, 2016).
hypercoagulable states (1 paper, 2016). "RGS10 thus represents a potential therapeutic target to control platelet activity and/or hypercoagulable states." (PMID 27829061, 2016). "For example, compounds enhancing RGS10 function may be effective for the treatment of hypercoagulable states, whereas RGS10 inhibitors could be developed for conditions associated with a bleeding diathesis." (PMID 27829061, 2016).
influenza (1 paper, 2021). An acute viral infection of the respiratory tract, occurring in isolated cases, in epidemics, or in pandemics; it is caused by serologically different strains of viruses (influenzaviruses) designated A, B, and C, has a 3-day incubation period, and usually lasts for 3 to 10 days. "The findings presented in this study show that RGS10 provides improved protection to the host against lethal influenza-stimulated lung inflammation and pathology, as loss of functional RGS10 protein leads to a significantly worse scenario upon IAV infection." (PMID 34912341, 2021). "Overall, these findings propose a novel, in vivo role for RGS10 in the respiratory immune system controlling myeloid leukocyte infiltration, viral clearance and associated clinical symptoms following lethal influenza challenge." (PMID 34912341, 2021). "Increased proinflammatory cytokine release in pulmonary macrophages due to RGS10 deficiency could exacerbate the early innate immune response to influenza, even if pulmonary macrophage numbers remain Rgs10-independent." (PMID 34912341, 2021). "Several cytokines with Rgs10-dependent BAL levels after influenza infection are also secreted by airway epithelial cells, not only by professional immune cells, further suggesting a potential role of epithelial Rgs10 in the process." (PMID 34912341, 2021). "Both cell types are known to express RGS10 that is down-regulated upon activation by microbial stimuli and to contribute to the anti-influenza immune response and related pathologies." (PMID 34912341, 2021). "Consistent with this, influenza-infected Rgs10-deficent lungs contain more neutrophil extracellular traps and exhibit higher neutrophil elastase activities than wild-type lungs." (PMID 34912341, 2021). "Based on this, we propose that RGS10 is a potentially important immune checkpoint of the early innate immune response to influenza that controls several leukocyte-recruiting and -activating molecules." (PMID 34912341, 2021). "Overall, the documented, Rgs10-dependent increases in the BALF cytokine and chemokine levels are likely responsible for the enhanced recruitment of monocytes and neutrophils to influenza-infected airways and contribute to the increased mortality and morbidity." (PMID 34912341, 2021). "While BALF levels of dendritic cells, T or B cells were not significantly influenced by Rgs10 deficiency upon influenza infection, CCL20 could have specifically attracted or stimulated Th17 cells known to be activated during influenza infection and to recruit neutrophils to the airways." (PMID 34912341, 2021). "Future studies will, however, include investigations on the role of RGS10 in nonlethal influenza infections to better understand its role under different infectious conditions." (PMID 34912341, 2021).
ischemia (1 paper, 2016). A hypoperfusion of the BLOOD through an organ or tissue caused by a PATHOLOGIC CONSTRICTION or obstruction of its BLOOD VESSELS, or an absence of BLOOD CIRCULATION. "The hyper-responsiveness of RGS10-deficient platelets conferred enhanced hemostasis (shortened bleeding time) and increased susceptibility to ischemia due to thrombosis in live mice." (PMID 27829061, 2016).
neuroblastoma (1 paper, 2013). Neuroblastoma (NB) is the most common solid, extracranial childhood tumor. "Our results showed that Rgs10-/- macrophages produced higher levels of pro-inflammatory cytokines including TNF, IL-1β and IL-12p70 in response to LPS treatment and exerted higher cytotoxicity on dopaminergic MN9D neuroblastoma cells." (PMID 24278459, 2013).
ovarian tumors (1 paper, 2013). "Further, future studies should further define differences in RGS10 expression in normal ovarian and fallopian tissues and ovarian tumors." (PMID 23533674, 2013).
Parkinson (1 paper, 2025). "Utilizing the Michael J. Fox Foundation Parkinson’s Progression Markers Initiative (PPMI) study we found that RGS10 levels are decreased in the CSF of individuals with PD compared to healthy controls and prodromal individuals." (PMID 39994765, 2025).
prostate carcinoma (1 paper, 2009). A carcinoma that arises from epithelial cells of the prostate gland. "In the gene pairs, our rules indicate that KIAA0762 is downregulated, while TUBB and RGS10 are upregulated in tumor tissue; however, there exists insufficient evidence to directly link the three genes with prostate cancer." (PMID 19874631, 2009).
respiratory infections (1 paper, 2021). "RGS10 also holds promise as a new, potential therapeutic target for respiratory infections." (PMID 34912341, 2021). "While these observations propose a role of RGS10 in controlling immune cell activation, it remains unknow whether RGS10 plays a role in limiting exacerbated immune responses in respiratory infections including lethal influenza A viral infection." (PMID 34912341, 2021).
Sepsis (1 paper, 2023). Sepsis is defined as life-threatening organ dysfunction caused by a dysregulated host response to infection. "It has been shown that RGS10 expression was repressed in LPS-induced AMs and that apicidin, a selective inhibitor of HDAC1-3, blocked this gene silencing and restored the inhibition of RGS10 expression level on the downstream signaling pathway of G proteins, thereby improving sepsis-associated ALI." (PMID 37175583, 2023).
type 2 diabetes mellitus (1 paper, 2025). A type of diabetes mellitus that is characterized by insulin resistance or desensitization and increased blood glucose levels. "Leeches may influence cellular immunity by modulating immune receptor activity, particularly through the activation of RGS10, CAPS2, and OPA1, thereby impacting the pathology of Type 2 Diabetes Mellitus (T2DM)." (PMID 40296871, 2025).
ulcerative colitis (1 paper, 2024). An inflammatory bowel disease involving the mucosal surface of the large intestine and rectum. "In colonic-inflammation-induced ulcerative colitis, for example, the deficiency in regulator of G-protein signaling 10 (RGS10) suppressed intestinal inflammation via inhibition of T helper cells 1 (Th1) and T helper cell 17 (Th17)-mediated immune responses." (PMID 39767678, 2024).